DZANK1 (double zinc ribbon and ankyrin repeat domains 1)
Description:
Involved in vesicle transport in photoreceptor cells.
Synonyms: C20orf12; C20orf84; FLJ10600; dJ568F9.2; FLJ30892; bA189K21.8; ANKRD64
Tractability: PROTAC: ubiquitination databases record sites on it.
Gene: Protein-coding gene on chromosome 20 (18,383,361 to 18,467,332, reverse strand). Ensembl gene ENSG00000089091.
Subcellular location: Cytoplasm, cytoskeleton, microtubule organizing center, centrosome; Cytoplasm, cytoskeleton, cilium basal body
Gene Ontology:
Molecular function: protein binding
Biological process: eye photoreceptor cell development
Cellular component: centrosome
Genetic constraint (gnomAD): Loss-of-function variants: 62 observed, 60.61 expected, observed/expected ratio (o/e) 1.02, 90% interval 0.83 to 1.26. The upper end of that interval is the gene's LOEUF score, 1.26, which puts it in group 5 of 6, group 1 being the genes least tolerant of losing a copy. Missense variants: 749 observed, 731.21 expected, observed/expected ratio (o/e) 1.02, 90% interval 0.96 to 1.09. Synonymous variants: 261 observed, 263.15 expected, observed/expected ratio (o/e) 0.99, 90% interval 0.9 to 1.1.
Homologues: Orthologues: chimpanzee DZANK1 (99% identical), macaque DZANK1 (96% identical), rabbit DZANK1 (81% identical), mouse Dzank1 (78% identical), dog DZANK1 (77% identical), rat Dzank1 (76% identical), pig DZANK1 (72% identical), guinea pig DZANK1 (57% identical), tropical clawed frog dzank1 (56% identical), zebrafish dzank1 (45% identical).
Diseases named in the same sentence as DZANK1 in open-access papers:
DZANK1 is named in the same sentence as 1 disease in open-access papers, as found by Europe PMC text mining. Sharing a sentence is not in itself a finding about the gene and the disease. The quoted sentences say what the papers report.
depression (1 paper, 2014). "Traits that map to the DZANK1 interval on chromosome 2 (139–150 Mb) include an assay for depression (GN11432, the tail suspension test) and ambulatory activity (GN12890)." (PMID 24523945, 2014).